ALDH2 (aldehyde dehydrogenase 2 family member)
Diseases named in the same sentence as ALDH2 in open-access papers (continued):
Sharing a sentence is not in itself a finding about the gene and the disease.
cancer (continued). "It is well known that the inactive ALDH2 carriers, specific to East Asian populations, have an increased risk of several cancer types because of increased exposure to acetaldehyde after alcohol consumption." (PMID 31204364, 2020). "ALDH2*2, a common dysfunctional polymorphism in the ALDH2 gene, has been linked to an increased risk of cancer and heart disease." (PMID 32932651, 2020). "Among these, polymorphisms in the ADH1B and ALDH2 genes are known to play a pivotal role in cancer development in combination with alcohol consumption." (PMID 32300124, 2020). "Further research is therefore needed to focus on the relationship between the ALDH2 SNP, DE and their associated cancer phenotypes." (PMID 29426835, 2018). "Many other studies from Japan, Taiwan, and China have overwhelmingly confirmed the significant association between ALDH2 enzyme deficiency and upper aerodigestive track (oropharyngolaryngeal, esophageal, stomach, colon and lung) cancer risk." (PMID 29552329, 2018). "In conclusion, we found that several types of cancer show a profile with a lower ALDH2 and a higher XRCC1 expression that is linked to a poor prognosis." (PMID 30088263, 2018). "This would mean that low ALDH2 expressing cancer cells are at a high risk of aldehyde overload if BER levels are not high enough." (PMID 30088263, 2018). "These numbers derived from an ALDH2-deficient human cancer model suggest markedly lower BMDL values for ACH (<0.1 mg/kg bw/day) than the ones calculated from studies on experimental animals (11–63 mg/kg bw/day)." (PMID 29303995, 2018). "For the high prevalence of the ALDH2 rs671 SNP, ALDH2 downregulation not only increases cancer risk but also influences cancer prognosis." (PMID 29426835, 2018). "The large number of epidemiological studies underlying this relationship make subjects with the ALDH2 genotype a solid and unique cancer model for the evaluation of acetaldehyde toxicity." (PMID 29342885, 2018). "Mutations in ALDH2, the enzyme required for acetaldehyde metabolism, are also associated with predisposition to cancer signifying its critical role in the removal of genotoxic metabolic intermediates." (PMID 28835508, 2017). "Genome wide association studies have demonstrated that genetic polymorphisms in ALDH2 are associated with many alcohol-related conditions, which has led to studies of the association between ALDH2 and various cancers and disease." (PMID 28052001, 2017). "The IARC working group further emphasized the strong evidence of acetaldehyde derived from alcohol metabolism as the mechanistic basis in causing upper aerodigestive track (UADT) cancers in individuals with ALDH2 deficiency." (PMID 28253921, 2017). "The ALDH2*2 allele is a risk factor for the development of many diseases and cancers, especially when combined with alcohol consumption." (PMID 28431562, 2017). "ALDH2 is the main enzyme responsible for the metabolism of acetaldehyde, which increases cancer risk." (PMID 29254255, 2017). "Many studies have investigated the role of ALDH2 polymorphism and its interaction with alcohol consumption in the development of various cancers." (PMID 28253921, 2017). "The link between cancer and another common functional variant in the ALDH2 gene, rs886205, is also controversial." (PMID 29166882, 2017). "A meta-analysis based on 51 case-control studies consisting of 16774 cases and 32060 controls was performed to evaluate the association between the ALDH2 Glu504Lys polymorphism and cancer risk." (PMID 25680115, 2015). "The association of the aldehyde dehydrogenases-2 (ALDH2) Glu504Lys polymorphism (also named Glu487Lys, or rs671) and cancers has been investigated." (PMID 25680115, 2015). "ALDH2 deficiency appears to be the most prevalent and powerful known genetic risk factor for cancer." (PMID 25831092, 2015). "The results from these GWA studies and our meta-analysis collectively suggest the importance of ALDH2 polymorphism carrying the susceptibility of cancer risks." (PMID 25680115, 2015).
cancer (continued). "The effect of the alteration of ALDH2 activity by Glu504Lys SNP on the risk of cancer has been shown to interact with lifestyle factors, especially alcohol consumption." (PMID 26491656, 2015). "Genome-wide association (GWA) studies had also been previously conducted on the association of ALDH2 gene with cancer risks." (PMID 25680115, 2015). "Cancer prevention is based on the identification of specific etiological factors, e.g. ALDH2 deficiency, achlorhydric atrophic gastritis, Helicobacter pylori infection, and group 1 carcinogenic agents." (PMID 25831092, 2015). "Associations between SNPs of MTHFR, MTR, MTRR, DNMT1, and ALDH2 genes and cancers of the esophagus, stomach, and liver." (PMID 25337902, 2014). "A deficiency of the ALDH2 enzyme in people carrying the ALDH2 Lys487 allele contributes to an elevated risk of cancer from alcohol consumption." (PMID 24881324, 2013). "A functional polymorphism in ALDH2 has been identified (rs671) to be associated with cancer risk, which lead to different activity of ALDH2 enzyme and is prevalent in Asians." (PMID 22675424, 2012). "The ALDH2*2 allele codes for an inactive ALDH2, and is closely associated with alcohol related cancers in the upper aerodigestive tract." (PMID 21672255, 2011). "Individuals with ALDH2 polymorphisms have a markedly reduced capacity to metabolize acetaldehyde, potentially leading to more complex and severe disease manifestations, such as malignant tumors, myocardial infarction, and dementia." (PMID 40943250, 2025). "Due to its diverse physiological and detoxifying activities, ALDH2 deficiency has been associated with a wide range of diseases, including cardiovascular and neurodegenerative disorders, alcohol-related liver disease, and cancer." (PMID 40558540, 2025). "ALDH2 deficiency has been linked to various human diseases, including certain cancers." (PMID 40558540, 2025). "Future work will involve leveraging this alcohol challenge assay to further phenotype human ALDH2 genetic variants in combination with supporting in vitro and cell culture studies to more precisely define the interplay between alcohol consumption, ALDH2 genetic variants, and cancer." (PMID 39075523, 2024). "Genetic variations such as the ALDH2 polymorphism, which is more prevalent in East Asian populations, may show different effects on the cancer risk caused by alcohol consumption." (PMID 39311360, 2024). "ROS, such as ACE induced by ALDH2-deficiency, can be neutralized and tolerated in cancer cells." (PMID 38292172, 2024). "ALDH2 in the mitochondria of liver cells is a crucial alcohol-metabolizing enzyme with substantial activity, capable of eliminating acetaldehyde, an intermediate product in alcohol metabolism associated with cancer and inflammation." (PMID 38338571, 2024). "ALDH2 polymorphisms is found to be related to cancer occurrence and development." (PMID 37589509, 2023). "However, not only are the ALDH2 variants but ALDH2 expression has been linked to cancer pathogenesis and progression." (PMID 37476181, 2023). "Besides, ALDH2 is a biomarker of cancer stem cells (CSCs) and is associated with proliferation, invasiveness, and multidrug resistance to chemotherapy reagents." (PMID 37589509, 2023). "We could not obtain itemized data on cancer metastasis, which limited further investigations of the roles of ADH1B and ALDH2 polymorphisms in the cancer progression and prognosis." (PMID 35670037, 2023). "In this hospital‐based case–control study, we determined the importance of the ADH1B rs1229984 C allele and ALDH2 rs671 A allele with regard to their association with a high risk of cancer of the larynx, pharynx, hypopharynx and nasal cavities, esophagus, and pancreas." (PMID 35670037, 2023).
cancer (continued). "These notions raised a hypothesis that cancer development in HBOC patients might be retarded or abrogated by the loss or decrease of ALDH2 function in cases with AA or GA genotypes, respectively." (PMID 36345163, 2023). "However, there are also several studies emphasize that ALDH2 overexpression or high activity is associated with cancer progression and multidrug resistance." (PMID 36694633, 2023). "Altogether, given the existence of alternative pathways, it is much likely that the influence of ALDH2 polymorphisms on NTG biotransformation in cancer cells may be rather limited." (PMID 37173331, 2023). "Based on this observation, it is plausible that mutations in ALDH2, a gene coding for aldehyde dehydrogenase to detoxify acetaldehyde, may elevate cancer risk in individuals with a heterozygous BRCA2 truncating mutation such as the BRCA2 p.K3326* mutation." (PMID 37943872, 2023). "The Flow char for selection of the study population (A), and the PheWAS Manhattan and QQ plots for ADH1B rs1229984 (B) and ALDH2 rs671 (C), respectively Brief Summary Our findings provide evidence of additive and synergic risks of the ADH1B and ALDH2 variants for alcohol‐related disorder and cancer." (PMID 35670037, 2023). "Furthermore, there is growing evidence of an association between ALDH2 deficiency and the development of cancers in the liver, stomach, colon, and lung." (PMID 36923641, 2023). "However, although there are many meta-analyses on the association between ALDH2 gene polymorphism and cancer risk, studies on the regulatory mechanism of ALDH2 involved in cancer pathogenesis and prognosis are still relatively scarce." (PMID 35269824, 2022). "Subjects with ALDH2*2 enzyme deficiency carries are at an alarmingly higher risk especially for UADT cancers associated with alcoholic beverages consumption, even with moderate consumption (two drinks in men and one drink in women per day; one standard drink = 14 g of alcohol)." (PMID 35330099, 2022). "Moreover, ALDH2 deficiency enhances acetaldehyde concentrations in saliva 2- to 3-fold and in gastric juice 5- to 6-fold, elevating the risk of cancer development compared to individuals with an active ALDH2 enzyme." (PMID 36430619, 2022). "However, less is known about the role or effect of ALDH2 deficiency in cancer progression and prognosis." (PMID 35330099, 2022). "Although these infectious agents are unlikely to be confounding factors in the associations between the studied genetic variants and cancer risks, whether they may interact with alcohol consumption and ALDH2 deficiency remains to be elucidated." (PMID 35048370, 2022). "ALDH2 polymorphisms are also linked to cancer occurrence and progression." (PMID 36144737, 2022). "The East Asian-specific ALDH2*2 missense mutation is a genetic risk factor for UADT cancer." (PMID 35330099, 2022). "In particular, the mutation of ALDH2 gene is closely associated with the risk of cancer." (PMID 36523602, 2022). "In addition to the direct effect of ALDH2 polymorphism, ALDH2-related aldehyde metabolites are also closely associated with cancers." (PMID 35517510, 2022). "ALDH2 is widely associated with cancer mediated by the metabolic disorder of alcohol and aldehydes, and it could be a possible prognostic biomarker for several types of cancer." (PMID 35269824, 2022). "Similarly, in humans, alcohol consumption and ALDH2-deficiency are strongly associated with the risk of various types of cancers, such as esophageal cancer." (PMID 35717470, 2022). "FBP1 and ALDH2 are both involved in a signaling pathway linked to cancer metabolism." (PMID 36144737, 2022). "We hope our analysis will inspire further epidemiological studies to determine whether these common ALDH variants increase the risk for a specific disease (e.g., cancer), as is the case for ALDH2." (PMID 34680056, 2021).
cancer (continued). "However, the cancer risk in the current or former flushers was substantially lower than the risk in ALDH2*1/*2 carriers in an alcohol-dependent population overall." (PMID 34310648, 2021). "We analyzed somatic mutations, CNV, and DNA methylation of ALDH2 across 33 cancer types." (PMID 35096916, 2021). "A study from Japan, which is another country with a high prevalence of ALDH2*2 allele carriers, reported that even light to moderate level of drinking was associated with an increased risk of cancer (OR for 10 drink‐years = 1.05; 95% CI, 1.04‐1.06 compared to never drinkers)." (PMID 32539207, 2020). "Because Asian flushers are at a higher risk for various types of cancer, guidelines including information about the genetic risk and a recommendation for genetic assessment (i.e., genotyping ALDH2) might be beneficial." (PMID 31146355, 2019). "Genetic polymorphisms of ALDH2 have been associated with a wide range of diseases and cancers." (PMID 30166580, 2018). "Such drugs could potentially have a great utility in reducing the risk of cancer or cancer recurrence, especially among the groups of high-risk individuals who are alcohol drinkers, cigarette smokers and carriers of ALDH2*2 allele." (PMID 28253921, 2017). "ALDH2 Glu504Lys polymorphism has also been shown to interact with the SNPs of other key enzymes in ethanol metabolism in the development of alcohol-associated cancers." (PMID 26491656, 2015). "Characteristics of studies included in ALDH2 Glu504Lys polymorphism and cancer risk." (PMID 25680115, 2015). "Stratification analyses of the ALDH2 Glu504Lys polymorphism on cancer risk." (PMID 25680115, 2015). "Considering the contradictory results of the previous studies on ALDH2 Glu504Lys polymorphism with different cancers, we conducted the present meta-analysis to evaluate the relation of ALDH2 Glu504Lys polymorphism with the overall cancer risk." (PMID 25680115, 2015). "Moreover, it is worth mentioning that the effects of the ALDH2*2 allele on alcohol-related cancers may be complex due to its direct carcinogenesis and indirect protective effect of alcohol avoidance." (PMID 36831600, 2023). "Thus, ALDH2 has special physiopathological significance, and its downregulation and inactivation have been associated with many health conditions, including cardiovascular diseases, neurodegenerative diseases, alcohol-related liver disease, and cancer." (PMID 36831600, 2023). "Additionally, the finding that the risk of cancer of the larynx, pharynx, and nasal cavities is associated with the ALDH2 rs671 GA/AA genotypes (OR = 1.19, p = 0.02) may be explained by the habit of alcohol consumption among these individuals." (PMID 35670037, 2023). "Carriers of the ALDH2*2 variant commonly present alterations in a number of blood biomarkers, clinical measurements, biometrics, drug prescriptions, dietary habits and lifestyle behaviors, and they are also more susceptible to aldehyde-associated diseases, such as cancer and cardiovascular disease." (PMID 35749303, 2022). "However, the clinical consequences or cancer risk to carriers of these additional ALDH2 variants is currently unknown." (PMID 35330099, 2022). "Importantly, appropriate analysis and interpretation of ALDH2‐rs671‐alcohol interactions offers the opportunity to assess the causality of alcohol and to investigate the role of alcohol‐derived acetaldehyde in the aetiology of certain cancers." (PMID 35048370, 2022). "The association of these variants with human disease has yet to be explored, but due to the decreased activity it is likely that these patients may be at risk for related diseases similar to ALDH2*2 variant carriers, such as cancer, cardiovascular disease and others mentioned in this article." (PMID 35749303, 2022).
cancer (continued). "Clinically, ALDH2 has great prospects in tumor diagnosis and can initially detect the human ALDH2 genotype; given whether the patient’s genes are susceptible to cancer, cases are given some reasonable treatment suggestions to achieve individual precision medicine." (PMID 36523602, 2022). "In addition, downregulation of ALDH2 was associated with malignant phenotypes of cancers." (PMID 35096916, 2021). "In addition, the deficiency of ALDH2 tends to suggest malignant phenotypes and adverse prognosis, which might enhance the precise diagnosis and timely intervention of cancer patients." (PMID 35096916, 2021). "Interestingly, despite ALDH2 polymorphism being closely related to many diseases such as cardiovascular and digestive diseases, the mutational events were extremely rare in cancers, and the mutation rate of most cancers were <1%." (PMID 35096916, 2021). "In order to understand why cancer cells are unable to prevent the induction of DPCs and other DNA damage, caused by the accumulation of reactive aldehydes, we carried out bioinformatics analyses of ALDH2 mRNA levels in different cancer types using the Oncomine® database." (PMID 30088263, 2018). "In addition, alcohol-related cancer patients carrying ALDH2*2 may be at higher risk for recurrence or developing second primary cancer and thus follow-up plan with more clinical visits may be required." (PMID 28253921, 2017). "The important role of ALDH2 indicated that the accumulation of styrene glycoaldehyde, a possible genotoxic intermediate of styrene, could account for the genotoxicity observed, and should be taken as an increased risk of cancer." (PMID 27224914, 2016). "Therefore, it is hypothesized that the genetic polymorphism in ALDH2 gene may be strongly correlated with the susceptibility to cancer, and a number of studies have investigated the association between ALDH2 Glu504Lys polymorphism and cancer risk." (PMID 25680115, 2015). "Further research is needed to elucidate the effects and mechanisms of ALDH2 in different tissues during the progression of cancer." (PMID 40968356, 2025). "The association between the ALDH2 and ADH1B genotypes and cancer risk varies across studies, and stratification based on alcohol consumption status is essential to clarify these discrepancies." (PMID 40943250, 2025). "Besides, the genetic ADH5 and ALDH2 deficiency in mice, a condition common among humans, leads to increased circulating levels of formaldehyde, which might then affect the bone marrow and cause cancer in the lymphatic tissue and solid organs." (PMID 41146278, 2025). "The sensor 21 can be used to detect acetaldehyde levels in cancer cells and monitor aliphatic aldehyde levels in the presence of both ALDH2 activators and inhibitors." (PMID 40171288, 2025). "DSF/copper overcomes resistance to microtubule inhibitors in cancer cells by downregulating ALDH2 expression, with copper enhancing the therapeutic efficacy of DSF." (PMID 40406488, 2025). "Conversely, ALDH2 contributes to the occurrence, progression, and treatment of various types of cancer and acts as a potential therapeutic target for cancer therapy." (PMID 40821701, 2025). "Drug discovery in cancer research has thus far been applied to ALDH1a1, ALDH1a3, and ALDH3a1 while drug discovery in substance abuse has focused on ALDH2, and discovery in the male contraceptive space has focused on ALDH1a1/a2 or RARα." (PMID 39133222, 2024). "Compared to the other ALDH isoforms, relatively few reports have been published on ALDH2 inhibitors, and fewer still have been tested as anti-cancer agents." (PMID 38612911, 2024). "To investigate the roles of ALDH2 in cancer development, we analyzed ALDH2 mRNA in normal and tumor tissues of various cancers in the TIMER database." (PMID 38292172, 2024). "Lower ALDH2 or HCDH expression is related to poor prognosis in patients with cancers such as KIRC and KIRP." (PMID 38911385, 2024).